MDM2 (MDM2 proto-oncogene)
Diseases named in the same sentence as MDM2 in open-access papers (continued):
Sharing a sentence is not in itself a finding about the gene and the disease.
Hyperglycemia (6 papers, 2017 to 2025). An increased concentration of glucose in the blood. "However, whether MDM2 is implicated in modulating GMC function during hyperglycemia is largely unknown." (PMID 28871126, 2017). "Altogether our data calls for further investigations to fully understand what role the MDM2/DROSHA pathway plays in controlling the maturation of angiomiRs under hyperglycemia." (PMID 33801773, 2021). "More importantly, the ubiquitination status of NICD1 was regulated by the level of MDM2 when knocking down MDM2 by siRNA, suggesting an ubiquitination modification role of MDM2 in GMCs under hyperglycemia condition." (PMID 28871126, 2017). "Furthermore, MDM2-mediated activation of Notch1 has been identified as a mechanism contributing to hyperglycemia-induced proliferation of glomerular mesangial cells and the accumulation of extracellular matrix (ECM)." (PMID 41203613, 2025). "Here, we explore whether MDM2 is involved in podocyte MC during hyperglycaemia." (PMID 28643424, 2017). "High glucose-induced GMC proliferation was also largely reversed by MDM2 depletion, indicating that MDM2 plays a critical role in GMC dysfunction under hyperglycemia condition." (PMID 28871126, 2017). "In the current study, we explored the role and mechanism of MDM2 in GMC proliferation and ECM accumulation under hyperglycemia condition." (PMID 28871126, 2017). "In our present study, we tested the hypothesis that MDM2 could drive GMC proliferation and ECM accumulation under hyperglycemia condition, and then explored its related downstream signaling pathways." (PMID 28871126, 2017).
invasive breast carcinoma (6 papers, 2016 to 2023). A carcinoma that infiltrates the breast parenchyma. "In conclusion, we have herein demonstrated that ERα expression associates with MDM4 and MDM2 gene expression in primary breast invasive carcinoma samples." (PMID 26909605, 2016). "The expressions of S100A6 and MDM2 in patients with invasive breast cancer were analyzed by immunohistochemistry." (PMID 37217945, 2023). "We observed that MDM4 and MDM2 mRNA expression was elevated in primary breast invasive carcinomas of luminal A and luminal B molecular subtypes, as compared to HER2-enriched, basal, and normal-like subtypes." (PMID 26909605, 2016). "However, immunopositive reaction for MDM2 was detected in 323 (61.6%) of the 524 invasive breast cancers." (PMID 31428819, 2019). "Using the Cancer Genome Atlas (TCGA) breast invasive carcinoma patient cohort, we have analyzed correlations between ERα status and MDM4 and MDM2 expression in primary, treatment-naïve, invasive breast carcinoma samples." (PMID 26909605, 2016). "In the present study, we utilized The Cancer Genome Atlas invasive breast carcinoma (TCGA BRCA) RNA-Seq gene expression dataset to analyze the expression of MDM4 and MDM2 mRNA in treatment-naive primary human breast invasive carcinoma samples." (PMID 26909605, 2016). "For patients with invasive breast cancer who received epirubicin and cyclophosphamide followed by docetaxel (EC-T), expressions of S100A6 and MDM2 were negatively correlated, and high expression of S100A6 suggested a higher rate of pathologic complete response (pCR)." (PMID 37217945, 2023). "For patients with invasive breast cancer who received epirubicin and cyclophosphamide followed by docetaxel (EC-T), the expressions of S100A6 and MDM2 were negatively correlated, and S100A6 was a predictive biomarker for the efficacy of neoadjuvant chemotherapy." (PMID 37217945, 2023).
ischemia (6 papers, 2017 to 2023). A hypoperfusion of the BLOOD through an organ or tissue caused by a PATHOLOGIC CONSTRICTION or obstruction of its BLOOD VESSELS, or an absence of BLOOD CIRCULATION. "The inhibition of PI3K-mediated phosphorylation of AKT or AKT knockdown promotes the retention of MDM2 protein in the cytoplasm, and it prevents Ser166 phosphorylation of MDM2, as well as IPC-mediated neuroprotection against ischemia-induced neuronal apoptosis." (PMID 34298892, 2021). "The specific AKT-mediated phosphorylation of MDM2 at Ser166 induced by IPC was confirmed by using a small interfering RNA (siRNA) specifically designed against AKT1 protein (siAkt), highly expressed in cortical neurons, and whose activity is essential for neuronal survival after ischemia." (PMID 34298892, 2021).
malignant glioma (6 papers, 2012 to 2021). A grade III or grade IV glioma arising from the central nervous system. "The deficiency of one or more MDM2 G4 binding/unwinding proteins may cause replicative stress that worsens or is at the root of the pathological genome amplification, as recently proposed for ATRX-deficient malignant glioma." (PMID 33410915, 2021).
metastatic melanoma (6 papers, 2010 to 2023). A melanoma that has spread from its primary site to another anatomic site. "Herein, we present the case of a 30-year-old male who, after undergoing multiple excision/grafting procedures for a giant CMN as a child, was diagnosed with an NRAS-mutant, MDM2-amplified metastatic melanoma more than 20 years later." (PMID 36569151, 2022). "Interestingly, alrizomadlin (APG-115), an MDM2 inhibitor, was recently studied in a phase II study in patients with unresectable or metastatic melanoma." (PMID 37175874, 2023).
myelodysplastic syndrome (6 papers, 2015 to 2025). A clonal hematopoietic disorder characterized by dysplasia and ineffective hematopoiesis in one or more of the hematopoietic cell lines.
seminoma (6 papers, 2016 to 2025). A radiosensitive malignant germ cell tumor found in the testis (especially undescended), and extragonadal sites (anterior mediastinum and pineal gland). "We found CN-Sig-5 to be associated with MDM2 expression in nonseminomas (p = 0.00008) and to be correlated with age at diagnosis in seminomas (p = 0.01)." (PMID 32366847, 2020). "Among them, we found the cell cycle- and CDK4/6-associated genes CCND2 (seminomas 9.8%, non-seminomas 16.8%), CDKN1B (P27; seminomas 15.3%, non-seminomas 16.4%) and MDM2 (seminomas 4%, non-seminomas 3.6%) commonly amplified in seminomas and non-seminomas." (PMID 32418994, 2020). "Notably, ecDNA contributed to amplification of oncogenes including KRAS (5 seminomas), KIT (1 seminoma), and MDM2 (1 seminoma, 2 non-seminomas)." (PMID 40568177, 2025).
serous ovarian cancer (6 papers, 2016 to 2025). "MDM2 mRNA expression was analyzed by microarray in 75 clear cell carcinomas, 13 normal tissues, and 16 high-grade serous ovarian cancers." (PMID 27659536, 2016).
solitary fibrous tumor (6 papers, 2022 to 2025). Solitary fibrous tumor (SFT) represents a diverse group of ubiquitous rare spindle cell neoplasms that may be benign or malignant and that most frequently arises from the pleura and peritoneum and rarely from other sites such as head and neck, liver and skeletal muscle. "The detection of MDM2 cluster amplification as in this case is a hallmark of DDLPS, aiding in its distinction from benign and low-grade mimickers, such as atypical spindle cell/pleomorphic lipomatous tumor or solitary fibrous tumor." (PMID 40211332, 2025). "Negative staining for MDM2 and CDK4, CD34 and STAT6, and c-kit and DOG1 led to the exclusion of dedifferentiated liposarcoma, solitary fibrous tumor (SFT), and GIST, respectively." (PMID 38739347, 2024).
Stroke (6 papers, 2021 to 2024). Sudden impairment of blood flow to a part of the brain due to occlusion or rupture of an artery to the brain. "In this context, we recently found that a single-nucleotide polymorphism (SNP) 309T>G in the MDM2 promoter determines the expression of MDM2 and, in turn, modulates the recovery of patients suffering from stroke." (PMID 34298892, 2021). "Further investigation into its mechanism reveals that Melatonin modulates ACSL4 ubiquitination and influences ferroptosis by boosting MDM2 expression, thereby leading to its therapeutic efficacy in treating stroke." (PMID 38289595, 2024).
systemic lupus erythematosus (6 papers, 2015 to 2024). An autoimmune multi-organ disease typically associated with vasculopathy and autoantibody production. "DNA induction of MDM2 promotes proliferation of human renal mesangial cells and alters peripheral B cell subsets in pediatric systemic lupus erythematosus." (PMID 37254181, 2023). "Our previous study indicated that autoantibody to MDM2 can be detected in systemic lupus erythematosus patients." (PMID 28147328, 2017). "Therefore, it is believed that CM-EV exhibited better therapeutic effects (as observed in lupus-specific miRNA expression and survival rates) through the regulation of MDM2 and histone modification." (PMID 39558370, 2024). "Since abnormally expressed proteins can induce autoimmune response, overexpression of MDM2 in lupus may trigger the production of autoantibody which may serve as a new serologic marker in SLE." (PMID 26090506, 2015). "One of our previous studies showed that autoantibody to MDM2 can be detected in systemic lupus erythematosus (SLE)." (PMID 28147328, 2017).
acute kidney injury (5 papers, 2016 to 2025). Sudden and sustained deterioration of the kidney function characterized by decreased glomerular filtration rate, increased serum creatinine or oliguria. "Doxycycline-induced deletion of MDM2 in tubular cell-specific MDM2-knockout mice Pax8rtTa-cre; MDM2f/f caused acute kidney injury with increased plasma creatinine and blood urea nitrogen and sharp decline of glomerular filtration rate." (PMID 27882940, 2016). "We conclude that MDM2 is essential for tubular epithelial cells homeostasis and survival and prevents acute kidney injury." (PMID 27882940, 2016).
autoimmune disease (5 papers, 2002 to 2025). A disorder resulting from loss of function or tissue destruction of an organ or multiple organs, arising from humoral or cellular immune responses of the individual to their own tissue constituents. "MDM2 splicing variants were present in tissues from alcohol- and autoimmune disorder-induced cirrhoses." (PMID 11953887, 2002). "The results indicate that the compounds MJ19 and MJ20 have the greatest effect on the induction of pro-inflammatory (IL6, IL8) and antiapoptotic (BCL2, MDM2) genes, suggesting their potential use in therapies for inflammatory and autoimmune diseases." (PMID 40725171, 2025). "Furthermore, Treg cells can suppress autoimmunity, and MDM2 is able to regulate the immunosuppressive activity of Treg cells, which provides a novel therapeutic target for autoimmune diseases." (PMID 32636834, 2020). "Therefore, our findings reveal that MDM2 in Treg cells could be a potential therapeutic target for treating autoimmune diseases and tumors." (PMID 32636834, 2020). "It is not clear why alcohol- or autoimmune disorder-induced cirrhosis but none of the HCV-induced cases showed MDM2 mRNA splicing." (PMID 11953887, 2002).
breast adenocarcinoma (5 papers, 2014 to 2021). "Expression of increasing amounts of MDM2 in human breast adenocarcinoma MCF‐7 cells results at a low amount of MDM2 in an increase in FOXO4 transcriptional activity whereas expression of high amounts of MDM2 show opposite effects." (PMID 29683489, 2018).
cholangiocarcinoma (5 papers, 2020 to 2026). A carcinoma that arises from the intrahepatic biliary tree (intrahepatic cholangiocarcinoma) or from the junction, or adjacent to the junction, of the right and left hepatic ducts (hilar cholangiocarcinoma). "Additionally, overexpression of MDM2 protein was observed in 38% of intrahepatic cholangiocarcinoma tumors and correlated with the presence of metastases (p < 0.01) and advanced tumor stage (p < 0.05)." (PMID 39199272, 2024).